CXCL1 (C-X-C motif chemokine ligand 1)
Diseases named in the same sentence as CXCL1 in open-access papers (continued):
Sharing a sentence is not in itself a finding about the gene and the disease.
melanoma (continued). "Melanoma‐derived EVs transfer the HSP90/p-IKKα/β complex and activate the IKK/IκB/NF-κB/CXCL1 axis in CAFs and promote angiogenesis." (PMID 37495566, 2023). "As was observed for melanoma cells, IFNγ treatment of Ptpn2 knockout CT26 and MC38 cells enhanced the expression of the IFNγ response genes Cxcl1, Ccl5, Stat1, Stat2, Stat3, Irf1, Pd-l1, Tap1, and Casp8, compared with IFNγ-treated control cells." (PMID 36968224, 2023). "Adipocytes cocultured with melanoma cells secreted higher IL6 and SerpinE1 levels and produced less CCL2, CXCL1, and angiogenic molecules." (PMID 37481560, 2023). "Some of the cytokines produced by human melanoma cells (IL-6, IL-8, CCL5 (RANTES), CXCL1–3 (MGSA-GROa-c), and monocyte chemotactic protein-1 (MCP-1/CCL2) are associated with tumour invasiveness and aggressiveness." (PMID 35334544, 2022). "Based on the GEPIA analysis 30, high level of CXCL1, CXCL2 and CXCR2 genes indeed often predicted the poor prognosis in melanoma patients." (PMID 35265199, 2022). "Spranger and colleagues identified a pathway in human melanoma, in which β-catenin produced by tumor cells suppresses the recruitment of CD103+ dendritic cells (DCs) by downregulating CCL3, CCL4, CXCL1, and CXCL2." (PMID 36366354, 2022). "CXCL1 mRNA levels and secretion increased in B16F10 melanoma treated with the CM of KLK6 overexpressed-RAW264.7 cells= compared to the CM of control vector-transfected cells." (PMID 36552865, 2022). "The involvement of PARP1 is important in melanoma tumorigenesis; in normal melanocytes, PARP1 is inactive and inhibits CXCL1 expression, while in melanomas PARP1 is active." (PMID 35054978, 2022). "Increased CXCL1 recruited PMN-MDSC and reduced natural killer T (NKT) cells in liver to form the pre-metastatic niche for melanoma and colorectal cancer liver metastasis in CCRK transgenic mice." (PMID 34067719, 2021). "The chemokines belonging to the growth-related oncogene (GRO) subgroup of CXC chemokines, GRO-α/CXCL1, GRO-β/CXCL2, GRO-γ/CXCL3, were first identified as growth factors of melanoma cell lines, before being attributed neutrophil chemotactic activity." (PMID 34503058, 2021). "The expressions of both CXCL1 and CXCL2 are increased by chronic hypoxia in PC-3 prostate cancer cells but reduced in SK-OV-3 ovarian adenocarcinoma and WM793B melanoma cells." (PMID 33467722, 2021). "In mouse models of melanoma, the combinatorial regimen of using the PLGA nanoparticles with the CXCL1 hydrogels exhibited superior tumor inhibition capability." (PMID 31818156, 2020). "In melanoma, PARP1 is mainly known to regulate NFκB activity, thus affecting CXCL1 cytokine transcription." (PMID 32455851, 2020). "CXCL1, also known as melanoma growth stimulating activity alpha (MGSA-α), is an autocrine melanoma growth factor." (PMID 30870978, 2019). "Upregulation of pro-angiogenic chemokine ligand CXCL1, CXCL2, and CXCL8 mRNAs in A-375 and SKMEL-28 melanoma sEVs was the most consistent finding." (PMID 30870978, 2019). "Upregulation of CXCL1, CXCL2, and CXCL8 mRNA in A-375 and SKMEL-28 melanoma sEVs was the most consistent finding." (PMID 30870978, 2019). "Increased CXCL1, CXCL2, and CXCL8 mRNA in melanoma sEVs, relative to primary melanocyte sEVs, was the most consistent finding." (PMID 30870978, 2019). "In this study, we were able to correlate the expression of the most consistently upregulated A-375 and SKMEL-28 melanoma sEV mRNAs (CXCL1, CXCL2, and CXCL8) to CXCL1, CXCL2, and particularly CXCL8 protein production at the sEV source cell level." (PMID 30870978, 2019). "The results demonstrate significantly increased production of CXCL1, CXCL2, and CXCL8 protein by A-375 melanoma cells compared to primary melanocytes." (PMID 30870978, 2019). "Neutrophils migrate into melanoma using the CXCR2 chemokine receptor in response to its ligands CXCL1, CXCL2, and CXCL5 expressed in melanoma." (PMID 30899263, 2019).
melanoma (continued). "CXCL1 binds to the CXCR2, which expresses on HSCs and neutrophils, and several types of cancer including melanoma, lung and pancreatic cancers." (PMID 29642635, 2018). "Among these, CXCL1, CXCL2, and CXCL5 can bind to chemokine receptor CXCR2, which is expressed on several melanoma cell lines and mediates signaling to significantly facilitate their growth in vitro and in vivo." (PMID 29541408, 2018). "The key chemokines involved in TAN recruitment to murine melanoma signal via the CXCR1 and CXCR2 axes, including CXCL1, CXCL2, CXCL6 and CXCL8." (PMID 28435677, 2017). "Malignant melanoma expresses and secretes various CXC chemokines, including CXCL1, CXCL2, CXCL3 (GRO family chemokines) and CXCL8 (IL-8)." (PMID 28129639, 2017). "Activation of melanoma cells by HFD includes induction of the NF-κB pathway, increased expression of adhesion molecules such as ICAM1 and chemokine synthesis, such as CXCL-1, -2 and -5." (PMID 27049717, 2016). "We provide evidence of FGF-2, CXCL-1, IL-8, and VEGF-A participation in the activity of melanoma cells on keratinocytes." (PMID 25560632, 2015). "Genes coding proteins such as FGF-2, VEGF-A, IL-8, and CXCL-1 have been found upregulated not only in tested BLM and NCSC but also in other melanoma cell lines (with the only exception of VEGF-A in primary culture of ascitic melanoma cells)." (PMID 25560632, 2015). "The reduction in the levels of chemokines CXCL1, CXCL2 and CXCL3 in melanoma results in a decrease in tumor angiogenesis and tumor growth, suggesting the importance of these chemokines in angiogenesis." (PMID 24259307, 2013). "For example, CXCL1-3, CXCL-8, and CCL-5 have been reported to favor melanoma growth and/or progression." (PMID 23342280, 2012). "Some studies of malignant melanoma have not shown a correlation between high CXCL1 expression and tumor characteristics." (PMID 38673949, 2024). "The combination of pharmacologic sEH inhibition and immune checkpoint blockade resulted in decreased gene expression of the pro-inflammatory cytokines Il-6, Cxcl1, Tnfα, Ccl2, and Ccl4 compared to control after 11 d of treatment in the B16F10 melanoma tumor tissue." (PMID 38330013, 2024). "However, CXCL1, CXCL2, CXCL3, CXCL5 and CXCL8 mRNAs were significantly upregulated in melanoma samples compared to benign nevi." (PMID 37270599, 2023). "To investigate whether CXCL1 can affect melanoma growth and metastasis, we subcutaneously or intravenously injected WT mice with B16F10 melanoma cells and then administered CXCL1 neutralizing antibody every other day for 10 days." (PMID 36552865, 2022). "The expression of CXCR2 in primary T cells enhanced migration toward both recombinant and melanoma-tumour-derived CXCL1 in vitro, and the surface expression of CXCR2 enhanced the accumulation of T cells in tumours in a mouse model of melanoma, improving tumour regression and survival." (PMID 35205725, 2022). "In addition, increased intratumoral CXCL1 level in RET transgenic mice, in contrast to CXCL5, significantly correlated with the accumulation of melanoma infiltrating PMN-MDSC." (PMID 33578808, 2021). "Aside from its direct effect on melanoma cells, CXCL8, along with other ligands of CXCR1 and CXCR2, namely CXCL1-3 and CXCL5-7, recruit innate cells, most notably neutrophils, which express the receptors CXCR1 and CXCR2 and are the “first responders” to tissue injury and damage." (PMID 34830780, 2021). "In contrast, it reduces the expression of CXCL1 and CXCL2 in WM793B melanoma cells." (PMID 33467722, 2021). "CXCL1/2/3/5/6/7/8 (receptors are CXCR2) have been demonstrated to be a promoter in tumor angiogenesis within a number of cancer types, including pancreatic cancer, melanoma, and prostate cancer." (PMID 34497764, 2021). "They concluded that blockade of CXCL1 and CXCL2 could improve immune tolerance at the tumor site by decreasing MoMDSCs in melanoma." (PMID 32707850, 2020).
melanoma (continued). "There is no CXCL1 expression in normal melanin cells, while the sustained expression of CXCL1 promotes malignant transformation and tumor growth of melanoma via autocrine, as well as microvascular growth into tumors in paracrine fashion." (PMID 33223508, 2020). "Furthermore, TTP depletion increased the production of several chemokines, such as C-X-C motif chemokine ligand 1 (CXCL1), CXCL2, and CXCL8 (also known as IL-8), which are involved in melanoma pathogenesis and angiogenesis." (PMID 30380668, 2018). "RT-PCR analysis showed that CXCL1 and CXCL8 were differently expressed in the analyzed cells with the overall lowest expression in WM164 and WM115 and the highest in WM873-1and in C8161 melanoma cells." (PMID 28129639, 2017). "Next, to test whether either CXCL1 or CXCL2 was necessary for enhancing the anti-tumor effects of HVJ-E, an anti-CXCL1 or CXCL2 antibody was intratumorally injected into melanoma-bearing mice 24 hours before the injection of HVJ-E+poly I:C." (PMID 27259252, 2016). "Furthermore, exposure of melanoma cells to HFD serum induced the pro-inflammatory NF-κB pathway and also enhanced the expression of CXCL1, CXCL2 and CXCL5." (PMID 27049717, 2016). "Also, the chemokines CXCL1, CXCL2 and CXCL3 have been shown to play a role in the growth of pancreatic cancer, melanoma, lung cancer, adenocarcinoma and gastric cancer." (PMID 24259307, 2013). "Previous studies reported that melanoma cells express high levels of IL8 and CXCL1 and their receptors CXCR1/2 and that IL8/CXCL1 signaling directly promotes cell migration of tumor cells, which may be relevant to tumor invasion and metastasis." (PMID 22719918, 2012). "Of note, CXCL1 and IL-8, the human ortholog of CXCL5, are expressed by human melanoma cells." (PMID 21980263, 2011). "As determined by qRT-PCR, treatment of M14 melanoma cells with Curcumin for several time periods (2, 4, 6, 15 and 24 h) did not affect CXCL1 expression." (PMID 20030852, 2009). "CXCL1 may not just be important in mechanisms in malignant melanoma tumors but also affect the whole body of a patient with malignant melanoma." (PMID 38673949, 2024). "In addition, the inflammatory response pathway was found to be enriched in MES samples as compared to MEL, accompanied by significantly high expression of CXCL1 and its receptor, CXCR2, as well as chemokine receptors CCR4 and CCR6, in melanomas characterised by the invasive gene signature." (PMID 36765773, 2023). "Increased levels of inflammation-related mRNAs, such as C-X-C motif chemokine ligand 1, 2 and 8 (CXCL1, CXCL2 and CXCL8) mRNAs, were also identified in melanoma-derived EVs compared to those derived from primary melanocytes, which may be related to a pro-inflammatory role." (PMID 36704194, 2022). "In addition, Western blot analysis showed that TNF-α and CXCL1 protein were detected in tumor tissues from WT mice injected with B16F10 melanoma but not in those from KLK6−/− mice injected with B16F10 cells." (PMID 36552865, 2022). "The mechanism of CIITA induction in melanoma is unknown, but MHC class II expression parallels the expression of chemokines CXCL-1 and CXCL-8 and the nuclear expression of NFκB p50 subunit, which are associated with tumor invasiveness and poor prognosis in melanoma." (PMID 24409178, 2013). "Western Blot results revealed that M14 melanoma cells treated for several time periods (6 h, 15 h, 24 h) with Curcumin (lanes indicated with "+") did not express and secrete less CXCL1 into their conditioned media than their respective un-treated control cells (lanes indicated with "-")." (PMID 20030852, 2009). "Given the potential role in melanoma progression, we analyzed whether the lack of effect of Curcumin on NFκB is transferred to the downstream target, CXCL1." (PMID 20030852, 2009).
melanoma (continued). "In addition, our study allows the identification of an immunosuppressive signature characterized by high GLI and low cytokine/chemokine expression (CCL7, CCL2, CCL20, CXCL8, CXCL1 and CXCL10), which could be used to stratify melanoma patients with poor survival." (PMID 39090759, 2024). "Furthermore, fibroblasts activated by melanoma cells showed upregulation of the MMPs’ expression mediators’ levels (pERK, p-p38, CD44, RUNX), enhanced secretion of lactate, several cytokines (IL8, IL6, CXCL1, CCL2, ICAM1), and proteins related to angiogenesis (GM-CSF, DPPIV, VEGFA, PIGF)." (PMID 35538545, 2022). "Similarly, CXCL1 secretion was not consistent, even if CXCL1 was shown to accelerate tumor growth, angiogenesis, and stromal recruitment during the metastatic process in melanoma, breast and colon cancer." (PMID 22253825, 2012). "RT-PCR and ELISA data showed that CXCL1 mRNA levels and secretion in B16F10 melanoma significantly increased on coculture with WT BMDMs but not with KLK6−/− BMDMs." (PMID 36552865, 2022). "Melanomas developed from cells lacking MyD88 showed an enhanced secretion of chemoattractant ligands such as CCL2, CXCL10 and CXCL1 and have an improved infiltration of macrophages to the tumor site." (PMID 28662055, 2017).
colitis (96 papers, 2009 to 2026). Inflammation of the colon. "Genes such as C3, Ccl2, Cxcl1, Ifi44, Lcn2, S100a8, and Tnf were strongly induced during colitis, mirroring previously reported inflammation-associated transcriptional responses." (PMID 40806068, 2025). "However, and in contrast, the DSS-induced colitis caused significantly increased levels of CXCL1, CCL2, CCL3, CCL11, G-CSF, and GM-CSF in Mcpt-4ΔCre mice as compared to Mcpt-4fl/fl mice." (PMID 40697820, 2025). "Moreover, severe mucosal damage caused by induced colitis resulted in low expression of CXCL1 due to damage to the intestinal epithelial cells." (PMID 35163326, 2022). "Another study revealed that early-life exposure to microbiota can induce microbial enduring and host changes that lead to colitis-associated cancer susceptibility, during which enhanced expression of CXCL1, CXCL2, and CXCL5 attracts G-MDSC to generate an immunosuppressive environment." (PMID 34689842, 2021). "Previous studies have corroborated these findings, demonstrating that inhibition of CXCL1 or STAT1 in murine models of ulcerative colitis alleviates colonic inflammation." (PMID 41406086, 2025). "Further ELISA and qRT-PCR results showed that the protein and mRNA levels of inflammatory factors IL1-β, IL6, G-CSF and CXCL1 in the colon tissue homogenates of KO colitis mice were significantly higher than those of WT mice." (PMID 41417165, 2025). "In our work, the defect of Mcpt-4 gene led to colitis mice producing higher levels of chemokines especially CXCL1, CCL2, CCL3, and CCL11." (PMID 40697820, 2025). "Reduced editing and Flna expression levels were associated with an increased expression of classical proinflammatory cytokines and chemokines like Il1b, Cxcl1, or Il6, which are typically induced during colitis." (PMID 40471139, 2025). "In animal models of ETBF-induced tumorigenesis, the BFT was shown to exacerbate colitis in tumorigenesis by promoting the production of the inflammatory cytokine interleukin-17A (IL-17A) and CXCL1 in the host." (PMID 39330861, 2024). "CXCL1 is a pro-angiogenic CXCL1 is a pro-angiogenic chemokine, and PGE2 can induce CXCL1 expression, increase MDSC infiltration in colitis-associated colorectal cancer mouse models, promote in vivo tumor growth and increase tumor micro vessel formation." (PMID 38717677, 2024). "Our data indicate that CAPE treatment decreases BFT-induced IL-8 (the human equivalent of CXCL1) expression by inhibiting NF-κB in intestinal epithelial cells, resulting in reduced inflammation in the large intestine during colitis and CRC." (PMID 39330861, 2024). "The Phgg-fed group exhibited elevated colonic levels of Cxcl1, both at the mRNA and protein levels, suggesting its potential role in the Phgg-induced exacerbation of colitis and CAC development." (PMID 39711544, 2024). "In this study, we showed that CAPE treatment reduced ETBF-mediated colitis by downregulating the expression of IL-17A and CXCL1 in mice." (PMID 39330861, 2024). "Our data suggest that the involvement of PAI-1 in the pathogenesis of colitis mainly affects CXCL1/CXCL5 and their receptor CXCR2, which are important for neutrophil recruitment and tissue injury." (PMID 37151884, 2023). "The expression of Il1a, Ccl5, Il1b, Ccl3, and Cxcl1 were significantly elevated in CD45+ cells from Il17b-/- colitis mice (P < 0.05)." (PMID 36814913, 2023). "Given that glial A2BR dependent signaling induces a sustained increase in CXCL1 during resolution, we tested if neutralizing CXCL1 during the resolution of colitis would protect barrier function." (PMID 35869148, 2022). "In the colitis group, the expression of CXCL1 was lower and the expression of CCL5 and CXCR2 was higher compared to the control group." (PMID 35163326, 2022). "Comprehensive bioinformatics analysis using RRA, WGCNA, and Cytoscape, as well as in vivo validation using a classic mouse model of colitis revealed CXCL1, IL1B, MMP1, and MMP10 as signature genes of active UC." (PMID 35392084, 2022).